CCDC6 (coiled-coil domain containing 6)
Diseases named in the same sentence as CCDC6 in open-access papers (continued):
Sharing a sentence is not in itself a finding about the gene and the disease.
cancer (continued). "Moreover, altered levels of CCDC6 protein in cancer cells seem to depend on the altered turnover of CCDC6 protein regulated by the de-ubiquitinase USP7." (PMID 28415632, 2017). "CCDC6 loss or low expression in different cancer models impairs RAD51 foci formation, limits γH2AX foci formation by modulating the activity of the histone phosphatase PP4C and sensitizes the cancer cells to PARPi treatment." (PMID 27884198, 2016). "In most cancers that harbor the CCDC6 gene rearrangements, the product of the normal allele of CCDC6 is either wholly absent or functionally impaired by a dominant negative mechanism." (PMID 25885523, 2015). "Recently, we have reported that the H460 NSCL cancer cells, that show low levels of CCDC6 protein, are sensitive to the PARP inhibitor olaparib, whereas H1975 cells, harboring high levels of CCDC6 protein, are resistant to olaparib and become sensitive when CCDC6 is knocked down." (PMID 25885523, 2015). "One of these un-annotated genes, Bc055324, is a predicted protein coding gene, which has a high co-expression ratio of more than 0.7 with the cancer genes Rad51 and Ccdc6, indicating this gene is increased in expression in >70% of the cases when Rad51 is increased in expression." (PMID 23039964, 2012). "The role of CCDC6 as a tumor suppressor gene in different types of cancers remains unclear." (PMID 36186907, 2022). "Additional molecular alterations in CCDC6 gene, recently reported in different primary tumors, might imply similar effects on cancer cell resistance to conventional anti-cancer therapy and possibly predict the efficacy of the combined treatment with PARPi in further patients." (PMID 31877762, 2019). "Therefore, we suggest that the clinical usage of USP7 inhibitors, by downregulating the CCDC6 levels, might increase the sensitization to olaparib and enhance the response to standard chemotherapeutics in combined therapy in cancer cells." (PMID 25885523, 2015). "Here, we report a critical role of FBXW7 in the control of CCDC6 homeostasis in mitosis by regulating its ubiquitin-proteasomal degradation and providing evidences that the CCDC6 post-translational regulation in the cell cycle may account for differences in cancer cells drug response." (PMID 25885523, 2015). "CCDC6 is a member of the coiled‐coil domain‐containing (CCDC) protein family located on human chromosome 10q21, which has garnered increasing attention in cancer research." (PMID 41035371, 2025). "For gene fusion, Pan Cancer 6 Fusion standard that had six types of fusions: TPM3-NTRK1, QKI-NTRK2, ETV6-NTRK3, EML4-ALK, CCDC6-RET, and SLC34A2-ROS1 was used." (PMID 38404964, 2024). "Next-generation sequencing targeting 520 cancer-related genes was performed on the pleural effusion samples and revealed 2 novel RET fusions LINCO1264-RET and SEMA5A-RET, concomitant with a common CCDC6-RET." (PMID 36451418, 2022). "We identified 14 cancer driver genes, including the most frequently altered KMT2C (100%), KNL1 (100%), NCOR2 (100%), and CCDC6 (93%) genes." (PMID 34245124, 2021). "Almost all the fusion transcripts reported in KuNG FU are specific for a single cancer type, however three fusions (BRD4-NUTM1, CCDC6-RET and EML4-ALK) were found across a variety of different cancer types." (PMID 33257674, 2020). "We also show for the first time that the first 101 aa of CCDC6 involved in the CCDC6 fusions reported in NSCLC, can functionally impair the HR DNA repair process and affect cancer cell sensitivity to selected drugs." (PMID 31877762, 2019). "Thus, if a role can be ascribed to CCDC6 in the activation of the EGFR signaling, the detection of CCDC6 impairment upon TK fusion could represent an indication for targeting EGFR in cancer therapy (Cerrato A, Di Domenico I, Morra F, Celetti A, manuscript in preparation)." (PMID 29455670, 2018).
cancer (continued). "Moreover, by using the same evaluation criteria, we identify new biomarkers whose impact on drug response spans multiple cancers, including SALL4, B2M, BAP1, CCDC6, ERBB4, FOXA1, GRIN2A, and PTPRT." (PMID 39083502, 2024). "Our pan-cancer analysis further substantiated these findings, demonstrating that the downstream effects of CCDC6 and PTK2 on cell function are likely pervasive in cancer beyond just HL, a finding consistent with prior evidence showing their broader roles in cancer progression." (PMID 39697539, 2024). "To further investigate CCDC6 expression in hepatobiliary cancers, we performed IHC analyses of 94 paraffin-embedded HCC tissues including both carcinoma tissues and their matched adjacent non-carcinoma tissues." (PMID 36186907, 2022). "Among the genes located in these regions, ETV1, CCDC6, and NCOA4 are known cancer critical genes." (PMID 32580154, 2020). "Therefore, in thefuture, it may be possible to combine these drugs or apply them sequentiallydepending on the expression patterns of USP7, CCDC6, and EZH2 in individual cases ofprostate cancer to provide novel forms of customized therapy." (PMID 32453339, 2020). "Our study indicates that the molecular alterations of CCDC6 by impairing the CCDC6 nuclear function may act as ‘BRCA like’ alterations, making cancer cells selective target of PARPi Olaparib which might help to overcome the resistance to the conventional anticancer therapy in NSCLC patients." (PMID 31877762, 2019). "Indeed, cancer cells defective for CCDC6 show an impaired HR process and switch to the non-homologous end joining process (NHEJ) to repair their DNA." (PMID 31877762, 2019). "Thus, patients carrying CCDC6/TK fusion may benefit of a combined therapy of TKI and PARPi in order to avoid selection of TKI resistant cancer cells." (PMID 29455670, 2018). "Using two different primer pairs that either bound within the RET kinase domain or flanked the CCDC6-RET fusion site, we confirmed by quantitative PCR that Lc2/ad cancer cells, but not several KRAS wildtype and mutant CRC cells, harbored the CCDC6-RET fusion kinase." (PMID 26078337, 2015).
neurodegenerative disease (1 paper, 2022). A disorder of the central nervous system characterized by gradual and progressive loss of neural tissue and neurologic function. "ADAM10 and CCDC6 were the shared causal genes for the psychiatric and neurodegenerative diseases at both the mRNA and protein levels." (PMID 35882878, 2022).
CCDC6 also shares sentences with these, for which no sentence is quoted: infection (6 papers); colon adenocarcinoma (2); colorectal adenocarcinoma (2); glioblastoma (2); head and neck cancer (2); abscess (1); adenocarcinoma (1); Alzheimer disease (1); astrocytomas (1); B-cell acute lymphoblastic leukemia (1); bacteremia (1); bipolar disorder (1); bladder tumor (1); breast fibrosarcoma (1); cervical cancer (1); chronic lymphocytic leukemia (1); Cirrhosis (1); CNS tumors (1); enteritis (1); esophageal carcinoma (1); glioma (1); head and neck squamous cell carcinoma (1); hepatoma (1); hypothyroidism (1); inflammatory bowel disease (1); leiomyosarcoma (1); lung (1); lung squamous cell carcinoma (1); lymphoma (1); mastitis (1).
A further 17 diseases each share a sentence with CCDC6 in 1 paper.